DOT1L (DOT1 like histone lysine methyltransferase)
Diseases named in the same sentence as DOT1L in open-access papers (continued):
Sharing a sentence is not in itself a finding about the gene and the disease.
leukemia (continued). "Indeed, potent small molecule inhibitors of DOT1L, developed by us and others, have been found to have selective activity against MLL leukemia." (PMID 26970896, 2016). "Therefore, combining POL5551 with newer targeted agents, such as inhibitors of BRD4 or DOT-1L in MLL-R leukemias and phosphoinositide 3-kinase (PI3K) and mTOR inhibitors in hypodiploid ALL and Philadelphia chromosome-like ALL, may improve outcome in these high-risk pediatric leukemias." (PMID 26360610, 2015). "Therefore, inhibition of DOT1L, in combination with DNA damaging chemotherapy, represents a promising approach to improving outcomes for MLL-rearranged leukemia." (PMID 24858818, 2014). "DOT1L, the only known histone 3 lysine 79 (H3K79) methyltransferase, has been reported to interact with MLL-AF10, and is required for initiation and maintenance of several types of MLL-rearranged leukemias, such as MLL-AF9 and MLL-AF6." (PMID 24858818, 2014). "Conditional knockdown of Dot1l in mice harboring the MLL-AF6 fusion inhibited leukemia progression, and the same group demonstrated that Dot1l knockout prevented initiation of leukemia harboring MLL-AF10." (PMID 23847761, 2013). "In other cases, pediatric leukemia research has led to novel targets that had not previously attracted attention; a notable example is the histone methyltransferase DOT1L." (PMID 23847761, 2013). "Furthermore, in human leukemias bearing chromosomal translocations at the mixed lineage leukemia (MLL) or clathrin assembly lymphoid myeloid (CALM) genes, mistargeting of DOT1L leads to transcript upregulation." (PMID 21291527, 2011). "Recent studies have shown that in mixed lineage leukemia, several MLL fusion partners, including MLLT10/AF10, may activate elongation of transcription by linking DOT1L to the pTEFb complex essential for transcription elongation." (PMID 21103407, 2010). "Consequently, by recruitment of DOT1L as well as the SEC via different mechanisms, KMT2A‐fusion proteins can modify chromatin architecture and directly drive transcriptional elongation at KMT2A‐target genes for the initiation and maintenance of leukemia." (PMID 39887730, 2026). "However, despite the use of DOT1L inhibitors in the clinic for patients with leukaemia, its role in NK cells and ILC1s has not been defined yet." (PMID 38962004, 2024). "Since the discovery of Dot1L as histone methyltransferase targeting on histone H3K79, great progress has been made in uncovering the role of this methylation modification in different physiological and pathological conditions, especially in the MLL-rearranged leukemias." (PMID 35986422, 2022). "Taken together, low dose MLL1 and DOT1L inhibitors downregulate different, yet partially overlapping sets of genes (with FLT3, MEF2C, and PIM1 in common), that are necessary for MLL-rearranged leukemia, consistent with the synergism arising from largely distinct pathways." (PMID 34263728, 2021). "We observed reductions in H3K79me2 and STAT5A phosphorylation after 9 days pinometostat treatment, suggesting that DOT1L inhibition may also reduce the viability of non-MLL-rearranged FLT-ITD leukemias through disruption of FLT3-ITD/STAT5A signaling." (PMID 34263728, 2021). "Furthermore, we couple the sc-Tiling with three-dimensional structural modeling and discovered a previously unrecognized self-regulatory domain in DOT1L that modulates the chromatin interaction, enzymatic activation, and therapeutic sensitivity in MLL-r leukemia." (PMID 34210975, 2021). "Inhibiting the enzymatic activity of DOT1L by genetic ablation or small-molecule inhibitors was sufficient to suppress leukemogenesis in preclinical models of MLL fusion leukemia, demonstrating a critical role for DOT1L in leukemia pathogenesis and validating DOT1L as a promising therapeutic target." (PMID 33562706, 2021).
leukemia (continued). "Given that DOT1L is essential both in development and normal hematopoiesis and given that a significant percent of MLL-rearranged leukemia patients are infants, it is important to develop an alternative, safer therapeutic strategy that does not inhibit key physiological functions of DOT1L." (PMID 33562706, 2021). "Similarly, pharmacologic inhibition of DOT1L’s methyltransferase function shows modest and delayed responses in vitro and in vivo when compared to genetic inactivation that demonstrated DOT1L’s essential function in MLL-rearranged leukemia." (PMID 33371192, 2020). "Disruptor of telomeric silencing 1-like (DOT1L), a histone methyltransferase specific for the lysine 79 residue of histone H3 (H3K79), was recently reported to promote the development of mixed lineage leukemia (MLL)-rearranged leukemia and the proliferation and metastasis of BC." (PMID 32244385, 2020). "Currently, it is not clear whether the molecular perturbations described in leukemia are relevant for the differentiation phenotypes described in other model systems, and whether DOT1L activity targets enhancers in physiological developmental settings." (PMID 33060580, 2020). "Among the HMTs, disruptor of telomeric silencing 1-like (DOT1L), a methyltransferase specific for the histone H3 lysine 79 residue (H3K79), was recently reported as mediating the development and maintenance of mixed lineage leukemia (MLL)-rearranged leukemia and TNBC metastasis." (PMID 33379275, 2020). "Given the unique dependence of MLL-FPs on aberrant SAM–dependent activating H3K79 methylation by DOT1L to maintain leukemic potential, we investigated perturbation of Met/SAM metabolism as a novel therapeutic strategy to disrupt abnormal activating epigenetic methylation driving MLL-R leukemias." (PMID 31717699, 2019). "In addition, we tested whether CCI-006 synergized with the DOT1L inhibitor EPZ-5676 (Pinometostat) that showed modest clinical efficacy in adult patients with advanced acute leukemias, including MLL-r leukemias." (PMID 30670779, 2019). "The histone methyltransferase (HMT) disruptor of telomeric silencing 1-like (DOT1L) has come to the forefront as a critical mediator of MLL-FP mediated leukemogenesis and has been shown to be required for the development, maintenance, and progression of MLL-R leukemias." (PMID 31717699, 2019). "Thus, DOT1L activity is not necessary for MLL-AF9-induced Myb transcription in this leukaemia cell line." (PMID 31882723, 2019). "Although the DOT1L methyltransferase inhibitor, pinometostat, has cell-inhibitory effect in cells and in vivo models of MLL-r leukemia, recent results from a phase I clinical trial indicated that the small molecule has only modest efficacy in treating MLL-r leukemias." (PMID 31157223, 2019). "Consistent with this paradigm, genetic deletion of DOT1L stops the leukemic transformation of hematopoietic stem cells (HSC) transfected to express MLL fusions, and new small molecule inhibitors of DOT1L are selectively toxic to MLL fusion driven leukemia cells in vitro and in xenograft models." (PMID 31717699, 2019). "In order to interrogate whether DOT1L has cancer-type-specific targets, we compared our results with another study that performed H3K79me2 ChIP-seq assays in a leukemia cell line MV411 with and without the treatment of the DOT1L inhibitor SGC094628." (PMID 29343685, 2018). "Furthermore, we investigated the role of DOT1L absence on cell growth in non-MLL arranged leukemia HL-60 and normal HPM cells." (PMID 29343685, 2018). "Furthermore, the DOT1L inhibitor EPZ-5676 could interact synergistically with DNA hypomethylating agents, such as azacitidine and decitabine, in MLL-rearranged leukemia cells." (PMID 28148257, 2017). "Therefore, DOT1L is an attractive target for therapy, resulting in the first selective DOT1L inhibitor EPZ-4777 to be synthesised with anti-tumor effects against murine models of MLL-rearranged leukemia." (PMID 28148257, 2017).
leukemia (continued). "Indeed, we found that under continuous exposure to EPZ-5676, the leukemia cells transduced with DOT1L KMT-targeting sgRNA #47, but not the control sgRNAs, were initially depleted and later recovered to >50% GFP positivity by day 30 in culture." (PMID 28231254, 2017). "Rather, similar to DOT1L inhibitors, a series of cellular events are required for LSD1 inhibitors to inhibit cell growth, which could include blocked H3K4 demethylation, downregulation of leukemia-relevant genes, and depletion of downstream effector proteins." (PMID 26970896, 2016). "DOT1L, the only known histone H3-lysine 79 (H3K79) methyltransferase, has been shown to be essential for the survival and proliferation of mixed-linkage leukemia (MLL) gene rearranged leukemia cells, which are often resistant to conventional chemotherapeutic agents." (PMID 24858818, 2014). "Following a demonstration that the activity of DOT1L is markedly enhanced by interaction of the enzyme with ubiquitinylated histone 2B, it has now been reported that proliferation of MLL-R leukemia cells was suppressed by knockdown of the ubiquitin ligase RNF20 that ubiquitinylates histone 2B." (PMID 23847761, 2013). "Interestingly, in KMT2A::MLLT3 rearranged MOLM13 cells the same analysis revealed predominant binding of DOT1L to promoter regions and no relevant association with putative enhancers indicating a function in MPN cells that is distinct from KMT2A-rearranged leukemia." (PMID 40781484, 2025). "Recently, more reports have focused on PPIs involving DOT1L epigenetic regulation because this targeted disruption not only ensures that the methylation activity of DOT1L is not affected but also has higher selectivity for leukemia cells than inhibition of DOT1L enzymatic activity." (PMID 35331314, 2022). "Therefore, inhibition of DOT1L by SYC-522 treatment shows that reducing DOT1L methyltransferase activity and its downstream targets MEIS1 and HOXA9, can promote differentiation and might represent a valuable approach for treating MLL-rearranged leukemia." (PMID 34698191, 2021). "However, whether lncRNAs could specifically play regulatory roles in the balance between self-renewal and differentiation in MLL leukemia or serve as effector molecules of DOT1L to affect the abnormal activation of HOXA genes has not been reported yet." (PMID 32552847, 2020). "Interestingly, gene pathways that were upregulated by MENIN/DOT1L inhibitors include a pathway for negative cell proliferation, which may contribute to their potent inhibition of MLLr leukemia." (PMID 27462455, 2016). "Although several novel compounds, such as inhibitors of DOT1L, LSD1 and BRD4, are in clinical trials, there have been no effective treatments for MLL1-r leukemia." (PMID 35395864, 2022). "Several novel agents such as DOT1L and FLT3 inhibitors that demonstrated selective targeting of KMT2A-r leukemia cells in preclinical models, have unfortunately failed to live up to their expectations in clinical trials." (PMID 35127484, 2021). "DOT1L inhibitors induce cell proliferation and apoptosis in MLL-rearranged leukemia cells but do not significantly inhibit cell proliferation or apoptosis in non-MLL-rearranged leukemia cells." (PMID 31590683, 2019). "Previous studies show another DOT1L inhibitor, EPZ004777, also inhibits the proliferation of leukemia cells without an MLL-rearrangement, although to a lesser degree as compared to MLL-rearranged cells." (PMID 24858818, 2014). "Taken together, these studies suggest that, in MLLr leukaemia without CBP translocation, CBP may participate in the super complex containing MLL-fusion and DOT1L, where CBP directly acetylates DOT1L to promote its stability." (PMID 38671157, 2024). "EPZ004777, the first SAM-competitive inhibitor of DOT1L, was able to kill biphenotypic (mixed-lineage) leukemia (MLL)-rearranged leukemia cells and prolong the survival time of mice with MLL-rearranged leukemia, but it had little killing effect on non-MLL translocated cells." (PMID 34050894, 2022).
leukemia (continued). "Consistently, we found that DOT1L inhibition reduced H3K79me2 levels and blocked MV411 and Molm14 MLL-rearranged leukemia cell growth in a dose-dependent manner but not the growth of human primary melanocytes (HPMs) or melanomas, including UACC62, A375, C021, C052, A04, and B16." (PMID 29343685, 2018). "Similarly, expression of WT DOT1L in MV411 leukemia increased H3K79 methylation, whereas mutant DOT1L proteins failed to do so." (PMID 29343685, 2018). "The result showed that DOT1L-targeted inhibition inhibited H3K79 methylation in all cell lines and specifically inhibited cell growth in leukemia cells with MLL translocations such as MV411, but not in melanoma cells, or leukemia without MLL translocations, such as HL-60." (PMID 29343685, 2018).
breast carcinoma (39 papers, 2014 to 2026). "DOT1L inhibition is sufficient to cause growth arrest in luminal breast cancer cells, which suggested that H3K79 methylation has functional significance in ER signaling." (PMID 35453496, 2022). "Histone methylase Disruptor silencing 1 like (DOT1L) has been implicated in breast cancer and lymph node metastasis." (PMID 32257110, 2020). "Based on the evidence that DOT1L is a co-factor and upstream regulator of ERα in breast cancer, we verified the possibility that ERα associates with DOT1L in PEO cells by co-immunoprecipitation experiments." (PMID 31689915, 2019). "In breast cancers, DOT1L is associated with poorer survival and aggressiveness, and DOT1L can cooperate with c-MYC and histone acetyltransferases to activate EMT and enhance cancer stem cell-like properties." (PMID 28804523, 2017). "Clinically, DOT1L expression is associated with poorer survival andaggressiveness of breast cancers." (PMID 26199140, 2015). "In the present study, bioinformatics analysis of a large breast cancer genetic database has implicated that DOT1L plays an important role in the malignancy." (PMID 25359765, 2014). "In silico analysis identified specific mutation in DOT1L sequence, which shows a high binding affinity for HLA isotype (HLA-A020), whose upregulation is associated with the initiation of immune response and a favorable prognosis in basal-like breast cancers." (PMID 35495127, 2022). "DOT1L is known to facilitate the aggressiveness of tumors by elevating the metastatic behavior of cancer cells and is implicated in lymph node metastasis of breast cancer." (PMID 36185256, 2022). "In our cohort, DOT1L was also associated withER-α negativity (P=0.046,χ2-test), as well as progesterone receptornegativity (P=0.014, respectively,χ2-test) and triple-negative breast cancer(P=0.027, χ2-test), whichare aggressive breast cancer subtypes." (PMID 26199140, 2015). "Collectively, our clinical, in vitro and invivo evidence indicated that DOT1L is a marker of aggressive phenotypein human breast cancer that is associated with a worse clinical outcome inER-negative breast cancer and advanced tumour progression related with EMT,invasion and metastasis." (PMID 26199140, 2015). "We first analyzed the expression of DOT1L in primary breast cancer tissues using RNA-seq data from the TCGA-BRCA dataset." (PMID 41299712, 2025). "Collectively, these results suggest that DOT1L inhibition activates tumor intrinsic innate immune responses in breast cancer cells." (PMID 41299712, 2025). "Through cooperation with c-Myc and p300 acetyltransferase, DOT1L promotes epithelial-mesenchymal transition (EMT) in breast cancer cells." (PMID 41299712, 2025). "ChIP-seq analysis of histone H3 lysine 4 trimethylation (H3K4me3), a marker of active transcription start sites (TSSs), revealed increased numbers of H3K4me3 peaks in breast cancer cells treated with a DOT1L inhibitor." (PMID 41299712, 2025). "Motif analysis demonstrated that IFN-stimulated response elements (ISREs) were significantly enriched around the H3K4me3 peaks in breast cancer cells treated with a DOT1L inhibitor." (PMID 41299712, 2025). "Expression of DOT1L is higher in breast cancers than in normal breast tissues, and inhibition of DOT1L suppresses proliferation of breast cancer cells." (PMID 41299712, 2025). "We also found that DOT1L inhibition suppresses ERBB2 expression in HER2-positive breast cancer cells." (PMID 41299712, 2025). "Genetic ablation of STING in breast cancer cells attenuated the activation of IFN signaling and growth suppression elicited upon DOT1L inhibition, suggesting the STING pathway contributes to the anti-breast cancer effect of DOT1L inhibition." (PMID 41299712, 2025). "In recent years, a number of studies have shown that DOT1L inhibition exerts anti-breast cancer effects through multiple mechanisms." (PMID 41299712, 2025).